EGF (epidermal growth factor)
Diseases named in the same sentence as EGF in open-access papers (continued):
Sharing a sentence is not in itself a finding about the gene and the disease.
rheumatoid arthritis (7 papers, 2008 to 2025). A chronic, systemic autoimmune disorder characterized by inflammation in the synovial membranes and articular surfaces. "Interestingly, other IFN-γ-induced KEGG pathways significantly attenuated by EGF included rheumatoid arthritis’ (FDR = 0.02) and ‘Epstein-Barr virus infection’ (FDR = 0.01)." (PMID 39924511, 2025). "It has been suggested that EGF is produced by the synovium in the initial stages of rheumatoid arthritis and that activation of EGF receptor signaling may be a causal factor in OA." (PMID 29610999, 2018). "Since synovial hyperplasia in rheumatoid arthritis (RA) resembles a tumor, involvement of the EGF/EGFR families in RA pathology has been implied." (PMID 18439312, 2008).
Sjögren’s syndrome (7 papers, 2010 to 2024). "A low salivary EGF level is also observed in patients with Sjögren syndrome, and the degree of EGF drop in saliva exhibits a significant correlation with the deterioration of their life quality." (PMID 30934722, 2019). "Previous studies by others have shown that EGF was decreased in tear fluid from Sjögren’s syndrome patients, and also in those patients with DED but without MGD." (PMID 20508732, 2010). "Interestingly, reduction of salivary EGF levels in Sjögren's syndrome patients seems to correlate with lowered oral health-associated quality of life." (PMID 36573202, 2022). "Our goal was to investigate the effects of epidermal growth factor (EGF) and interferons (IFNs) on signal transducer and activator of transcription STAT1 and STAT4 mRNA and active phosphorylated protein expression in Sjögren’s syndrome cell culture models." (PMID 38542139, 2024). "Epidermal growth factor (EGF) is secreted by lacrimal glands into tears, is measurable in the tears of mice, and significantly lower tear EGF concentrations have been found in murine models of Sjögren syndrome." (PMID 29438346, 2018). "STAT4 mRNA expression decreased 48 h after EGF treatment in A253 cells, immortalized salivary gland epithelial cells iSGECs nSS2 (sicca patient origin), and iSGECs pSS1 (anti-SSA negative Sjögren’s Syndrome patient origin)." (PMID 38542139, 2024).
ulcerative colitis (7 papers, 2012 to 2025). An inflammatory bowel disease involving the mucosal surface of the large intestine and rectum. "In contrast, clinical reports suggest that intravenous epidermal growth factor (EGF) enema can improve left‐sided semicolonic ulcerative colitis." (PMID 40641492, 2025). "Olsalazine significantly increased the contents of IL-2, IL-10, IL-22, TGF and EGF in ulcerative colitis rats, and significantly decreased the scores of DAI, CMDI, HS and the contents in IL-7, IL-17, TNF-α, IL-1β and IFN-γ when compared with the model group." (PMID 37610966, 2023). "For example, short-term treatment with epidermal growth factor (EGF) enemas has proven beneficial in ulcerative colitis patients." (PMID 25954931, 2015). "However, at sites of injury, luminal EGF can access these receptors, as demonstrated by the finding that EGF-containing enemas were effective in healing distal ulcerative colitis." (PMID 34132332, 2021). "EGF promotes wound healing in animal models of ulcerative colitis." (PMID 22937258, 2012). "It was suggested that olsalazine has a therapeutic effect on ulcerative colitis induced by DSS in mice, and the mechanism may be related to the increase of IL-2, IL-10, IL-22, TGF, and EGF and the decrease of the expression of IL-7, IL-17, TNF-α, IL-1β, and IFN-γ." (PMID 37610966, 2023).
acne (6 papers, 2021 to 2025). An inflammatory process of the sebaceous glands which is characterized by comedones, nodules, papules and/or pustules on the skin. "Aside from treating acne, EGF has also been used to treat skin melasma and is known to be non-invasive (Lyons, Stoll & Moy, 2018)." (PMID 39308805, 2024). "After 4 weeks of EGF cream application, a significant improvement in inflammatory acne lesions and a reduction in the occurrence of AAS have been observed in a previous study." (PMID 39212099, 2024). "In recent years, recombinant human epidermal growth factor (rhEGF) has also been frequently reported for its application in the treatment of acne scars." (PMID 39212099, 2024). "aFGF, bFGF, KGF-2, EGF, and among others, are proven to delay aging, promote whitening (Smit, Vicanova & Pavel, 2009), remove acne and other spots, moisturize, as well as eliminate wrinkles, and brighten the skin." (PMID 39308805, 2024). "Particularly, EGF alone reportedly can improve acne and acne scars." (PMID 39212099, 2024). "For example, recombinant human epidermal growth factor (rhEGF) is used in anti-acne creams." (PMID 39308805, 2024). "Meta-analysis of the gene expression profiles of whole acne tissue samples and EGF- and EGF+PA -treated SZ95 sebocytes showed that the EGF+PA co-activation of sebocytes may also have implications in disease." (PMID 34025636, 2021). "Moreover, the prominent induction of genes, such as PTGS2, CXCL8, IL6, IL1B, matrix metalloproteinase 1 (MMP1) and NLRP3, even raised the possibility that EGF and PA may be involved in the pathogenesis of acne." (PMID 34025636, 2021). "Moreover, a possible interaction with testosterone also suggested that at the time of puberty, EGF may lead to SG hypertrophy and thus be involved in the development of acne." (PMID 34025636, 2021). "The findings that sebocytes treated with both EGF and PA, while conserving their enhanced proliferation and increased lipogenesis, also acquired a prominent inflammatory gene expression profile may have further implications in understanding acne development." (PMID 34025636, 2021). "Treatment with topical epidermal growth factor after ablative fractional CO2 laser is safe and improves the clinical appearance of atrophic acne scars." (PMID 38381492, 2024). "Clustering the identified genes, showed that in the EGF+PA-co-treated sebocytes not only IL1 but also IL17 signaling, characteristic both for SG-rich healthy skin and for acne-involved skin, was induced." (PMID 34025636, 2021).
brain cancer (6 papers, 2013 to 2025). A primary or metastatic malignant neoplasm affecting the brain. "We will also discuss the integrated role of calcium channels and anoctamins in regulating calcium-mediated signalling pathways, such as epidermal growth factor signalling, to promote brain cancer cell growth and migration." (PMID 36497413, 2022). "In human brain cancer, exogenous EGF significantly enhances the formation of neurosphere cultures, while inhibition of EGFR tyrosine kinase activity potently inhibits sphere formation." (PMID 23620784, 2013). "For EGF pathway studies, these tissues have provided a variety of useful tumor and drug screening models, aging models, colon stem cell models, brain cancer, and cell proliferation models." (PMID 28178204, 2017). "PKM-mediated phosphorylation of histone H3 plays a critical role in the epidermal growth factor (EGF)-induced expression of cyclin D1 and c-Myc, which further promotes tumor cell proliferation in brain cancer." (PMID 37291128, 2023).
chordoma (6 papers, 2013 to 2024). Chordomas are rare malignant tumors arising from embryonic remnants of the notochord in axial skeleton. "Further studies are warranted to determine the role of EGF and these lncRNA in dural penetration of chordoma." (PMID 32533822, 2020). "Expression of 10 lncRNAs and mRNAs, and epidermal growth factor mRNA with two identified lncRNAs were subsequently verified by qRT-PCR in chordoma tissues." (PMID 32533822, 2020). "Therefore, together with the data presented herein, these findings strongly suggest that EGF was activated during the process of dural penetration in chordoma." (PMID 32533822, 2020). "Next, we analyzed the expression of EGF mRNA and the lncRNAs ABCC6P1 and AL078621.4 located in the lncRNA-mRNA co-expression network to explore whether EGF was regulated by these differentially expressed lncRNAs in dural penetration chordoma." (PMID 32533822, 2020). "The expression of p‐EGFR in chordoma may be explained on the basis that epidermal growth factor (EGF) ligands are direct targets of T17, the expression of which is considered to be critical in the growth of this tumour." (PMID 27102572, 2016). "We activated EGFR with EGF (20 ng/ml) or MET with HGF (20 ng/ml) treatment in UCH1 and C24 chordoma cells." (PMID 24621885, 2014). "Chordoma with serious dural penetration highly expressed EGF and AKT3 and show evidence of EGFR activation suggesting that RTK inhibitors may be useful for the treatment of dural invasion in chordoma." (PMID 32533822, 2020). "Although not explored in our xenograft, EGF and TGFα were reported to be highly expressed in 22 chordoma samples (100%) in a previous study." (PMID 24260133, 2013). "The EGF mRNA and lncRNA AL078621.4 were down-regulated, while lncRNA ABCC6P1 was up-regulated in no dural penetration chordoma samples." (PMID 32533822, 2020). "We observed that EGFR (fold change: 2.652), MET (fold change: 4.676), AKT3 (fold change: 3.703) and EGF (fold change: 11.094) which is a ligand of EGFR, were down regulated in chordomas without dural penetration." (PMID 32533822, 2020). "Additionally, mRNA for EGF and its regulatory lncRNAs levels of ABCC6P1 and AL078621.4 in chordoma tissues with serious dural penetration or without dural penetration were detected by RT-qPCR." (PMID 32533822, 2020).
fibrosarcoma (6 papers, 2013 to 2020). A malignant mesenchymal fibroblastic neoplasm affecting the soft tissue and bone. "By competing for AR/Src Association, the S1 peptide prevents the EGF mitogenic signaling in fibrosarcoma cells." (PMID 24130806, 2013). "PIBF also binds the promoter region of epidermal growth factor (EGF) gene in human fibrosarcoma cells." (PMID 28168193, 2017).
inflammatory bowel disease (6 papers, 2009 to 2025). A spectrum of small and large bowel inflammatory diseases of unknown etiology. "In conclusion, using Lactobacillus paracasei 27-2 as an oral delivery vector to express trefoil factor and epidermal growth factor shows great potential as a novel strategy for treating inflammatory bowel disease." (PMID 40284867, 2025).
liver cirrhosis (6 papers, 2017 to 2021). "The study interpreted an association between EGF gene polymorphism and HCC progression in liver cirrhosis via modulation of EGF levels." (PMID 30050894, 2018). "In our cohort, EGF liver and serum values were low and did present slightly higher levels in the BA patients with postoperative rapid liver cirrhosis." (PMID 34062967, 2021). "The EGF gene polymorphism genotype significantly correlated with EGF levels and conferred high risk of HCC development in patients with liver cirrhosis." (PMID 33297335, 2020). "EGF-EGFR signaling pathway has been found to be involved in liver cirrhosis and HCC." (PMID 32322693, 2020). "Epidermal growth factor (EGF)-EGF receptor (EGFR) signaling pathway plays key roles in both HCC and liver cirrhosis." (PMID 32322693, 2020).
lymph node metastasis (6 papers, 2009 to 2025). "The existence of EGF in GC has been found to be linked with the extent of gastric wall invasion and lymph node metastasis." (PMID 40296906, 2025). "The association analysis showed a relationship between EGF levels and lymph node metastasis (p = 0.004)." (PMID 34115785, 2021). "Within the oncological population, low serum EGF values are associated with the presence of lymph node metastasis." (PMID 34115785, 2021). "Serum EGF was significantly associated with the presence of lymph node metastasis and a trend to significance was found between serum EGF and tumour size." (PMID 34115785, 2021). "Serum EGF was significantly associated with lymph node metastasis." (PMID 34115785, 2021). "In the present study, we observed EGF A61G polymorphism was related to the tumor size and lymph node metastasis in CRC patients, indicating that this SNP may be a diagnostic marker for CRC patients with bigger tumor size and lymph node metastasis." (PMID 31053624, 2019). "Serum EGF was associated with lymph node metastasis (p = 0.004) but not with sex (p = 0.753), age (p = 1.00), TNM stage (p = 0.191) or tumour size (p = 0.077)." (PMID 34115785, 2021). "The presence of lymph node metastases, however, correlated with increased levels of several CAC such as VEGF (p = 0.02), VEGFR-1 (p = 0.006), PDGF-AA (p = 0.04), PDGF-BB (p = 0.0008), Ang-1 (p = 0.004) and EGF (p = 0.03)." (PMID 21729304, 2011).
metabolic syndrome (6 papers, 2017 to 2025). A cluster of metabolic risk factors for CARDIOVASCULAR DISEASES and TYPE 2 DIABETES MELLITUS. "Assessing urinary secretion of proinflammatory cytokines and epidermal growth factor can help in detecting early development of metabolic syndrome-associated renal dysfunction." (PMID 31886287, 2019). "Based on our assessment, urinary secretion of proinflammatory cytokines and epidermal growth factor positively correlated with metabolic changes in the kidney, a finding that may be useful in detecting the early development of metabolic syndrome-associated renal dysfunction." (PMID 31886287, 2019).
metastatic cancer (6 papers, 2013 to 2022). A carcinoma which has spread from the original site of growth to another anatomic site. "Epidermal growth factor (EGF) binding to its receptor (EGFR) has been identified as a potent chemoattractant stimulus for metastatic cancer cells." (PMID 24921075, 2014). "Recently it was reported that cofilin is implicated in cell migration in various cells such as smooth muscle cells and metastatic cancer cells and EGF induces this cell behavior." (PMID 23374291, 2013). "Activations of the TGF-β and Wnt pathways as well as secretions of EGF, MMPs, and VEGF are detected in the invasive fronts of metastatic cancer cells." (PMID 26572077, 2015).
osteoporosis (6 papers, 2017 to 2025). A condition of reduced bone mass, with decreased cortical thickness and a decrease in the number and size of the trabeculae of cancellous bone (but normal chemical composition), resulting in increased fracture incidence. "Furthermore, 36 hub genes of XLGB, such as EGF, EGFR, MTOR, MAPK14 and NFKB1, were considered potential therapeutic targets, suggesting the underlying mechanisms of XLGB acting on osteoporosis." (PMID 32620113, 2020). "GO and KEGG enrichment revealed PTH, NOTCH, FGF, EGF and CD59 pathways were significantly up-regulated in all parathyroid subpopulations in osteoporosis patients." (PMID 40496565, 2025). "Different pathways interaction analysis revealed that osteoporosis patients had higher levels of NOTCH, PTH, FGF, and EGF pathway whereas non-osteoporosis patients had highest level of NRG pathway." (PMID 40496565, 2025).
pancreatitis (6 papers, 2006 to 2024). Inflammation of the pancreas. "It was shown lately that blockade of EGF/EGFR attenuates pancreatic tumorigenesis induced by KRASG12D or pancreatitis, which supports the essential role of EGF signaling in PDAC." (PMID 28388589, 2017). "It has been shown that pancreatic acini from MMP7 knockout mice failed to undergo ADM in a pancreatitis model as well as in response to EGF activation." (PMID 38731942, 2024). "A series of studies confirmed EGF and EGFR upregulation in different pancreatitis models." (PMID 24212642, 2011).
Papillary thyroid cancer (6 papers, 1988 to 2025). "Gene expression modulation of BER and EGF signaling was assayed in starved human thyroid follicular epithelial Nthy-ori 3-1 cells and starved papillary carcinoma cell line TPC-1 after short term treatments (15 and 30 min), with H2O2 [10 mM], EGF, PD, LY alone or combined." (PMID 35269445, 2022). "For thyroid tumorigenesis, two main human in vitro models are available: primary cultures of human thyrocytes treated with TSH or EGF/serum as models for autonomous adenomas (AA) or papillary thyroid carcinomas (PTC) respectively, and human thyroid tumor derived cell lines." (PMID 25375362, 2014). "We suggest that the epidermal growth factor or other ligands for the c-erbB and c-erbB2/neu receptors may contribute to the development and/or maintenance of the malignant phenotype of papillary carcinomas of the thyroid." (PMID 3390372, 1988). "However, we note that SS may also play a protective role against TC through the inhibition of epidermal growth factor (EGF), a growth factor that plays an important role in the growth and differentiation of papillary carcinoma of the thyroid gland." (PMID 39928612, 2025). "Papillary thyroid cancer model TPC-1 did not express p-EGFR under any of the tested conditions (data not shown), whereas ErbB2 protein was always expressed and particularly increased after PD and EGF alone treatments." (PMID 35269445, 2022).
periodontal disease (6 papers, 2012 to 2025). "Given the importance of EGF in periodontal diseases, the investigation of genetic polymorphisms that may affect its transcriptional activity can provide important information on its function in periodontal diseases." (PMID 32477838, 2020). "In this regard, some reports have found different biological markers in the gingivo-crevicular fluid (GCF): elevated levels of Prostaglandin E, IL-1β, IL-6, TNF-α and epidermal growth factor (EGF) have been found in GCF during tooth movement or periodontal disease." (PMID 28179886, 2017). "We also examined the expression of EGF and its receptor EGFR that were profoundly modified during periodontal disease." (PMID 28748038, 2017). "Therefore, the balance between EGF and EGFR could constitute an important mechanism of regulation during the pathogenicity process of periodontal diseases, as observed with enzymes such as cathepsins and matrix metalloproteinases with their natural inhibitor counterparts." (PMID 28748038, 2017).
polycystic kidney disease (6 papers, 2010 to 2023). A usually autosomal dominant and less frequently autosomal recessive genetic disorder characterized by the presence of numerous cysts in the kidneys leading to end-stage renal failure. "Many studies have described the importance of EGF in polycystic kidney diseases as well as the role of EGF in cell proliferation, including in tubular epithelial cells." (PMID 30670929, 2018). "Two genes, EGR1 (up-regulated) and polycystic kidney disease 1-like (down-regulated), were commonly regulated in both Ishikawa H and Hec50co cells in response to EGF at 12 h." (PMID 20579378, 2010). "Our data suggest that EGF promotes calcium influx through this channel and subsequently enhances cell proliferation rate in orpk cilia (-) cells suggesting that this pathway may play a role in polycystic kidney disease." (PMID 23977387, 2013). "The expression levels of EGF and MCP1 were derived from microarray experiments on 13 renal cysts of different sizes, 5 minimally cystic tissue (MCT) from five PKD1 human polycystic kidneys and 3 normal renal cortical samples as control tissue." (PMID 36342644, 2023).
rectal cancer (6 papers, 2017 to 2025). A primary or metastatic malignant neoplasm that affects the rectum. "All cell lines, except MDA-MB-231 cells and DiFi rectal carcinoma, responded robustly to EGF stimulation by phosphorylating ERK1/2." (PMID 33883672, 2021). "Therefore, appearing of EGFR and its ligand EGF as crucial elements of rectum cancer is not a surprising finding." (PMID 30774817, 2018). "However, in patients with rectal cancer, TGFα levels, but not EGF levels, increased during cetuximab treatment, and this increase was correlated with T downstaging." (PMID 27933395, 2017).